IL2 (interleukin 2)
Diseases named in the same sentence as IL2 in open-access papers (continued):
Sharing a sentence is not in itself a finding about the gene and the disease.
colitis (continued). "Furthermore, although the DSS colitis model has been widely used to evaluate IL-2-based therapies, colitis can also be induced in immunodeficient mice lacking T and B cells using this model." (PMID 36261022, 2022). "Previously, we reported that LD IL-2 may be an effective therapy to treat IBD based on our results whereby LD IL-2 induced human Treg cell expansion and attenuated experimental colitis in immune humanized NSG mice expressing human HLA-DQ8 in a setting devoid of murine MHCII." (PMID 33717161, 2021). "Whether HLA restriction is required for human Treg cells to ameliorate colitis following LD IL-2 therapy has not been demonstrated." (PMID 33717161, 2021). "We also showed that the symptoms of colitis were not reverted even after IL-2 activity was reduced." (PMID 32308767, 2020). "Our experiments demonstrated that low-dose IL-2 ameliorates DSS-induced intestinal tissue damage by restoring intestinal barrier integrity and exerting an inhibitory effect on the PI3K/AKT and NF-κB pathways in vivo, thereby protecting the intestinal epithelium against DSS-induced colitis." (PMID 32308767, 2020). "Additionally, after the long-term administration of low-dose IL-2 (14 days and 21 days), the symptoms of colitis induced in mice by DSS were efficiently relieved without detrimental effects in other organs." (PMID 32308767, 2020). "Neither patient had evidence of CTLA-4 antibody-related colitis prior to starting HD IL-2 therapy." (PMID 27660706, 2016). "Therefore, our data provide new hints for an immune-regulating rather than immune-activating role of IL-6 in the colitis model of IL-2−/−-mice suggesting that IL-6 in the absence of TNF-α, IL-12 and IFN-γ exerts anti-inflammatory effects." (PMID 18545662, 2008). "Therefore, tissue‐prevalent mast cells stimulated by a combination of IL‐3 and IL‐33 would secrete high levels of IL‐6, but not IL‐2, and represent potential mediators of the negative regulatory role of IL‐3 in colitis‐mediated immune responses by induction of RORγt+ Tregs." (PMID 33427298, 2021). "B. vulgatus induces colitis in HLA/B27-β2m rats, but does not induce inflammation in other colitis models (e.g., IL-10−/− or IL-2−/− mice), which makes it difficult to assess whether this bacterium has colitogenic activity in a complex community in IL-10−/− mice." (PMID 31281321, 2019). "Here we use mice lacking calcineurin B (encoded by Cnb1) or IL-2 (encoded by Il2) in CD11chighMHCII+ cells, and show that calcineurin–NFAT–IL-2 signaling in intestinal CD11chighMHCII+ APCs prevents spontaneous chronic intestinal inflammation in acute and chronic models of induced colitis." (PMID 29549257, 2018). "While our current study highlights the therapeutic potential for LD IL-2 in treating patients with IBD, one limitation is that colitis induction by TNBS does not require human cells, which is in contrast to what we had previously observed." (PMID 33717161, 2021). "Using a translational humanized mouse model, LD IL-2 expands human Treg cells and is protective against TNBS-induced colitis that is independent of CD4+ HLA restriction." (PMID 34421921, 2021). "In this study, we provide evidence demonstrating that combined delivery of IL-2 immunocomplexes and anti-IL-5 mAb is highly effective at expanding Foxp3+ Treg cells in the absence of eosinophilia and ameliorating DSS-induced colitis in mice." (PMID 30930900, 2019). "This view is supported by the fact that IL-2 and IL-2-receptor knockout mice develop spontaneous colitis, which is thought to be due to the absence of CD4+CD25+ T regulatory cells (Treg), dependent on the presence of IL-2 for their suppressive function." (PMID 25505551, 2014). "Importantly, these data show that LD IL-2-induced Treg expansion and protection against TNBS-induced colitis was independent of Treg cell HLA-restriction." (PMID 33717161, 2021).
colitis (continued). "IL-2-REH elicited cell type-dependent differences in gene expression and provided mixed therapeutic results: showing benefit in the in vivo mouse dextran sulfate sodium (DSS) model of colitis, but no therapeutic efficacy in a transfer colitis model." (PMID 34003116, 2021). "We previously reported that CD8+CD103+ Treg induced ex vivo with TGF-β1 and IL-2 (CD8+CD103+ iTreg), regardless of Foxp3 expression, displayed potent immunosuppressive effect on Th cell response and had therapeutic effect on Th cell-mediated colitis." (PMID 29441062, 2018).
depression (151 papers, 2006 to 2026). "The association between inflammation and depression was initially discovered when multiple studies found that administering IL-2 and IFN-gamma to patients triggered depressive symptoms such as anhedonia and fatigue." (PMID 40573262, 2025). "Elevated plasma IL-2 at 24 h was associated with more severe post-concussive symptoms, while elevated IL-10 at 6 months correlated with greater depression and PTSD symptoms." (PMID 38397895, 2024). "First, it was reported that depression is associated with a chronic low-grade inflammatory response, and depressed patients have elevated levels of inflammatory cytokines such as interleukin-2 and interleukin-6, which are associated with decreased BMD." (PMID 36348273, 2022). "In contrast, IL-2 treatment attenuated and even reversed depression- and anxiety-like behaviors by normalizing the deficiency of monoamine neurotransmitters and the increase in neurotransmitter metabolism in the hippocampus and amygdala." (PMID 36430328, 2022). "On the one hand, depression is associated with increased levels of inflammatory cytokines (e.g., interleukin-2 and interleukin-6), and studies have suggested that these inflammatory markers are associated with decreased BMD." (PMID 35413849, 2022). "Raised levels of C-reactive protein and pro-inflammatory cytokines viz. interleukin-2 (IL-2), IL-6, interferon-γ, tumour necrosis factor-α, in the patients’ serum are markedly associated with psychotic syndromes i.e., mania, depression, etc5." (PMID 33637732, 2021). "Our findings that change in sleep time was inversely associated with anxiety, depression, and serum cytokine levels (IL-2, IL-1β, IL-6, TNFα) are in keeping with the consensus of these reviews." (PMID 33598780, 2021). "The “usual suspects” associated with depression tend to be elevated interleukins (ILs), interferons (IFNs) and acute phase proteins, including IL-1β, IL-6, IL-2, IFN-γ, tumour necrosis factor alpha (TNF-α) and C-reactive protein (CRP)." (PMID 34816138, 2021). "Development of depression is also associated with elevated circulating concentrations of inflammatory biomarkers; for example, proinflammatory and antiviral cytokines (IL-2, TNF-α and IFN-α) have been associated with flu-like and depressive symptoms." (PMID 25237578, 2014). "IL-2 influences monoaminergic neurotransmission in the CNS and is often linked to psychological diseases such as depression, or anxiety disorders." (PMID 23717619, 2013). "Some studies have shown that major depression is associated withdysregulation of immune mediators, such as the rise in interleukin (IL)-1β,IL-6, IL-12, soluble IL-6R, IL-2, soluble IL-2R, IL-1Ra, and IFN-γ (Kaestner etal." (PMID 18317531, 2007). "As IL-2 was found to be positively associated with major depressive disorder, probably, IL-2 might also be correlated with anxiety disorders like GAD, as MDD and GAD are highly co-morbid themselves and thus might share common pathophysiological factors." (PMID 38902708, 2024). "Of note, neuroinflammation has furthermore been implicated in the pathophysiology of depression, whereas increased inflammatory markers, such as C-reactive protein (CRP) or interleukin-2 (IL-2), have been specifically described to be more associated with the atypical subtype of depression." (PMID 38172332, 2024). "Indeed, higher IL-13 levels are associated with more severe depression and a higher number of suicide attempts, and elevated levels of IL-2, TNF-a, and IL-8 are associated with depressive symptoms in clinical studies." (PMID 39297528, 2024). "Inflammatory biomarkers (IL-6 and IL-2) have been linked to depression." (PMID 36506019, 2022). "Likewise, elevation of IL-2 is implicated in the pathogenesis of neuropsychological conditions like depression and schizophrenia, although it is required for normal hippocampal function or BDNF signalling." (PMID 33985854, 2021).
depression (continued). "In addition, the reduction of inflammatory cytokines, such as interleukin 2, as causative agents for anemia, can be an influencing factor in depression." (PMID 31363389, 2019). "In addition, the intake of EM reduced the abundance of Ruminococcaceae promoting the production of cytokines such as IL-1β, IL-2, and IL-6, Helicobacter inducing chronic inflammation and gastric cancer, and Alistipes causing serotonergic imbalance, anxiety and depression." (PMID 39572022, 2024). "Inflammatory cytokines like IL-1, IL-2, and IL-6 have been shown to predict treatment outcomes in treatment-resistant depression." (PMID 40370590, 2025). "The increase in pro-inflammatory cytokines IL-6 and IL-2 affects depression and anxiety in a neuromodulatory way, mediating the neurochemical, neuroendocrine, and behavioral aspects of mental health disorders." (PMID 40563433, 2025). "There were also trends observed for genetic variations in IL1β and IL2 and their interactions with child adversity and depression." (PMID 41009999, 2025). "Parallels can be drawn between the outcomes of this study and two recently published studies in which low dose IL-2 (ld IL-2) was used in the treatment of unipolar and bipolar depressed patients." (PMID 39867848, 2025). "Furthermore, increased levels of IL-2 have been linked to the degradation of the tryptophan enzyme, a precursor to serotonin synthesis, via the indoleamine 2,3-dioxygenase immune pathway, producing neurodegeneration and initiating anxiogenic and depressive disorders." (PMID 38941031, 2025). "At 1 month after enrollment, the severity of depression was related to IL-1β (B 0.75, P = 0.04), IL-2 (B 1.41, P = 0.01) and IL-4 (B 0.91, P = 0.01)." (PMID 38459460, 2024). "Elevated levels of other inflammatory cytokines such as Interleukin-1 beta (IL-1 β), Interleukin-2 (IL-2), and Interleukin-6 (IL-6) have also been observed in patients with major depressive disorder compared to healthy controls." (PMID 38959212, 2024). "In bipolar depression, IL-6 seems to be the predominant cytokine, IL-4 dominates in the euthymic state, and IL-2, IL-4, and IL-6 are prevalent in the manic state, while patients with unipolar depression mainly have elevated TNF-α, IL-6, and sIL-2R." (PMID 37510730, 2023). "Proinflammatory mediators, particularly interleukin (IL)-2, IL-6, IL-12, and tumor necrosis factor-alpha (TNF-α) have been linked to the progression of depression in past studies." (PMID 37353760, 2023). "One study has shown that interferon gamma and interleukin 2 can trigger depression when used therapeutically." (PMID 37069633, 2023). "The level of IFN-γ, IL-4, and IL-2 were significantly higher in HC group than that of the depression group." (PMID 35722555, 2022). "In BD depression, IL-6 is the predominant cytokine, in euthymic state it is IL-4, and in manic episode it is IL-2, IL-4, IL-6, while patients with unipolar depression have mainly elevated TNF-α, IL-6 and soluble IL-2 receptor (sIL-2R)." (PMID 36294388, 2022). "Consistent with this, the present study found that the suppression of M1 response by IL-2 can also decrease IDO enzyme activity, which restored the deficiency of monoamine neurotransmitter levels and eventually attenuated depression-like behaviors." (PMID 36430328, 2022). "Several mechanisms have been proposed to link obesity and depression, including a mild level of chronic inflammation characteristic of obesity, chronically increased proinflammatory interleukin (IL-2) levels, and leptin signaling." (PMID 36615803, 2022). "IL-2, a T-cell growth factor, was negatively correlated with depression in patients with acral melanoma, and with a low QOL in non-acral melanoma with TNM stages 0 and I, in our study." (PMID 36405903, 2022). "Lastly, our study was unable to evaluate some immune markers and cytokines previously linked to WNV infection such as IL-2, IL-4, IFN-B, TLR-3, IL-11, and IL-18, as well as some previously linked to depression such as IL-18 and NFκB." (PMID 35745504, 2022).
depression (continued). "IL-2 attenuated depression- and anxiety-like behaviors and normalized the neurotransmitter concentration and the activity of the IDO enzyme, astrocytes and microglia through restoring both balances, but it did not decrease the CORT concentration." (PMID 36430328, 2022). "An association between IL-2, IL-6, IL-8, TNF-α and VEGF levels and the severity of depression have been reported." (PMID 36045388, 2022). "Previous studies with major depressive disorder, schizophrenia, and generalized anxiety disorder showed that higher levels of IL-1β, IL-2, IL-6, and CCL2 were related to the severity of psychiatric symptoms." (PMID 35504954, 2022). "Studies have shown that Rg1 reduced the levels of IL-1β, TNF-α, caspase-1, IL-2, IL-6 and IL-18 via the suppression of Connexin43 (Cx43) ubiquitination in depression." (PMID 36010610, 2022). "Treg promoter IL-2 (1500UI/0.1 mL/day) was used to treat a mouse model of depression induced by chronic unpredictable mild stress (CUMS)." (PMID 36430328, 2022). "Studies have shown that depression is related to the expression of a variety of molecules, including IL-6, IL-2, IL-1β, TNF-α, and C-reactive protein (CRP)." (PMID 36010610, 2022). "At baseline, TNF-α (F = 36.699, p < 0.001), IFN-γ (F = 8.907, p < 0.001), IL-4 (F = 66.256, p < 0.001), and IL-2 (F = 9.162, p < 0.001) levels in the depression group were significantly different from those of healthy controls." (PMID 35722555, 2022). "Hyperactivation of the hypothalamic–pituitary–adrenal (HPA) axis and continuous increase in glucocorticoid levels in patients with depression inhibited the immune response and increased the serum levels of proinflammatory cytokines IL-6 and IL-2." (PMID 36506019, 2022). "In people with MS with comorbid fatigue and/or depression, there are reported increased serum and CSF concentrations of the pro-inflammatory cytokines, such as interleukins (IL-1a, IL-1b, IL-2, IL-6), TNF-α and IFN-γ." (PMID 35242093, 2021). "The influence of IL-2 on the occurrence of depression symptoms is evidenced by the development of depressive symptoms in people and animals to whom it was administered." (PMID 34575258, 2021). "Detecting increased concentrations of IL-17 and IL-2 in patients with depression can contribute to a better understanding of its pathomechanism." (PMID 33498653, 2021). "In the present study, many anti-depressant targets of EMO against depression were associated with the inflammatory response such as IL6, TNF, IL10, CRP, IL1B, CTLA4, ALB and IL2." (PMID 34051074, 2021). "In conjunction with measures of pregnancy-specific anxiety and depression, serum biomarkers (IL-2, IL-6, IL-10, IL1-B, TNF-α, CRH, CRP, and cortisol) were analyzed for each trimester throughout pregnancy." (PMID 34360332, 2021). "Multiple therapeutic targets were mediated by active ingredients of XYS, such as IL2, IL4, IL6, IL10, and STAT3, which are involved in immune and inflammatory responses closely associated with depression." (PMID 32256358, 2020). "Based on the univariate analysis of the GLM, we found significant differences in the years of education, cytokines (IL-1β, IL-2, IL-6, IL-12p70, IL-17A, IFNγ, TNFα, IL-10, and IL-13), and depression severity (indicated by the PHQ) among the groups." (PMID 32703187, 2020). "First, we found that the baseline levels of IL-10, IL-12p70, IL-13, IL-17A, IL-1β, IL-2, IL-23, IL-5, IL-6, IL-7, and MIP-1β were associated with depression symptoms." (PMID 32699226, 2020). "In the first mechanism, DHA and EPA can lead to decrease in production of proinflammatory cytokines, such as tumor necrosis factor (TNF)-α42, interleukin (IL)-1β, IL-2, and IL-6, which are determined by eicosanoid discharge and related to depression." (PMID 31383846, 2019). "Taken together, these results suggest that the interactions of diagnosis and BMI for depression have an effect on IL-2 levels." (PMID 31450770, 2019).